EZH2 (enhancer of zeste 2 polycomb repressive complex 2 subunit)
Diseases named in the same sentence as EZH2 in open-access papers (continued):
Sharing a sentence is not in itself a finding about the gene and the disease.
tumor (continued). "HEIH interacts with EZH2, resulting in increased binding of EZH2 to and H3K27 trimethylation of p16 promoter, downregulating the expression of this tumor suppressor." (PMID 38203767, 2024). "USP21 is known to deubiquitinate and stabilize several transcription factors such as YY1, FOXM1, EZH2, Nanog, and GATA3, promoting cancer cell proliferation, migration, and invasion and in vivo tumor growth." (PMID 39305962, 2024). "According to immunoblotting, lowered MELK and EZH2 expression and elevated LATS2 expression were observed in tumour tissues of nude mice injected with H1975 cells transduced with sh‐MELK." (PMID 38652219, 2024). "The expression of DNMT3A increased significantly when EZH2 was knocked down; CCL22 and CCR4 were downregulated in tumor tissues, and EMT-related protein expression also changed consistent with in vitro results." (PMID 39513112, 2024). "It acts by recruiting EZH2 to catalyze H3K27 trimethylation, leading to the suppression of downstream tumor suppressor genes." (PMID 38600608, 2024). "We then confirmed the target specificity of DYB‐03 in vivo and showed that tumor growth was slowed by double knockdown of HIF‐1α and EZH2 in A549, similar to the inhibitory effect of DYB‐03 on parental cells." (PMID 38072662, 2024). "The widely studied methyltransferase, enhancer of zeste homolog 2 (EZH2, the subunit of multi-comb inhibitory complex 2 [PRC2]), whose inhibitors have been used in tumor therapy, participates in gene expression silencing by catalyzing H3K27me3." (PMID 38581056, 2024). "To gain insight in the molecular consequences of EZH2 inhibition and the increased sensitivity to the combination in BAP1 depleted cells, we performed RNA sequencing (RNA-seq) on primary tumor cell lines treated with EZH2 inhibitor." (PMID 38054839, 2024). "Conversely, treatment with inhibitors led to an increase in H3K27me3 levels in FAT1 knocked out cells, supporting the view that CAMK2 activation can inhibit EZH2 and PRC2 activity in tumor cells." (PMID 38600608, 2024). "Under hypoxic conditions, however, PER2 levels decrease due to degradation, disrupting the inhibitory function of EZH2 on EMT genes and increasing tumor invasiveness." (PMID 38911968, 2024). "Lnc-DANCR knockdown prevents EZH2 from binding to the SOCS3 promoter, leading to SOCS3 upregulation, which in turn inhibits tumor growth." (PMID 39830662, 2024). "It was demonstrated that EZH2 expression was positively correlated with VEGF-A expression and AKT phosphorylation, and EZH2 promoted tumor growth via the VEGF-A/AKT signaling pathway." (PMID 38347129, 2024). "EZH2 negatively correlates with type I and III interferons and CD8+ T cell infiltration in NSCLC, altering the tumor microenvironment and inhibiting NSCLC response to programmed death 1 (PD1) blockade." (PMID 38525426, 2024). "High mRNA expression of both EZH2 and DOT1L in NB tumour samples correlated with the poorest patient survival." (PMID 39501501, 2024). "Besides, recent studies found that dietary and herbal compounds, such as apigenin and a synthetic derivative of curcumin called CDF (a novel curcumin-derived synthetic analogue), could simultaneously inhibit HIF-1α and EZH2, reducing cancer invasiveness and improving tumor prognosis." (PMID 38911968, 2024). "Tumor-bearing mice treated with Bm@PT/Enz-miR26a showed significant fluorescence of SFRP1 and decreased fluorescence of EZH2, WNT5A, and AR compared to other groups." (PMID 38566211, 2024). "More recently, studies in several cancer types have shown inhibition of epigenetic regulators (LSD1, EZH2, BET proteins) can enhance the anti-tumor immune response of anti-PD1 therapy." (PMID 38183103, 2024). "In view of our findings indicating the activation of STAT3 signaling pathway through the degradation of SUZ12 and EZH2 mediated by SUMOylated HSPA9, we investigated the role of STAT3 in MUL1-induced tumor inhibition effects." (PMID 39113711, 2024).
tumor (continued). "Ratnam and colleagues found that blocking EZH2 activity in human GBM cells with GSK126, a global EZH2 methyltransferase inhibitor with good BBB penetrance, led to upregulation of CXCL9 and CXCL10 chemokines and subsequently elevated tumor infiltrating T cells." (PMID 39409893, 2024). "Further, EZH2 bound to TNK2-AS1 silenced the gene coding for CELF2 (CUGBP Elav-like family member 2) and exerted tumor-promoting effects through activation of the PI3K/Akt pathway." (PMID 38473229, 2024). "Studies have indicated that EZH2 is upregulated in PTC, and its expression positively correlates with tumor staging." (PMID 38890707, 2024). "The tumor biopsies of PDX-P3 indicated a highly elevated Myc and EZH2 gene expression and 4-fold EGFR gene amplification." (PMID 38553638, 2024). "The expression of EZH2 and DOT1L were further assessed for correlations across patient tumours from the two large databases." (PMID 39501501, 2024). "Analysis of EZH2 using the TCGA database confirmed that EZH2 was also highly expressed in LUAD tissues and correlated with poor prognosis and tumor stage." (PMID 39013911, 2024). "Targeting polycomb demethylases has not been well developed clinically for cancer therapy compared to EZH2 targeting, with a limited number of preclinical reports of GSK-J4 having anti-tumor activity." (PMID 39482699, 2024). "Combined targeting of EZH2, MYC and YAP/TAZ can, therefore, effectively de-repress expression of tumor suppressors and concurrently repress the expression of oncogenic pathways, to ultimately inhibit tumor growth." (PMID 39455556, 2024). "Researchers have found that miRNAs regulate the expression of EZH2 and ATM genes, promote tumor cell proliferation and invasion." (PMID 38605642, 2024). "EZH2 has been targeted pharmacologically in various tumor types with the small-molecule inhibitor GSK126, a highly selective EZH2 inhibitor that competes with S-adenosyl-L-methionine binding." (PMID 38886296, 2024). "The results above suggested that DYB‐03 also exerts its tumor suppressive effect in vivo by acting on HIF‐1 and EZH2." (PMID 38072662, 2024). "Through transcriptome sequencing of CCA models with knockout of EZH2 and SUZ12, respectively, we identified SFRP1, a gene that plays a tumour suppressor role in CCA." (PMID 38050190, 2023). "In a study performed by Yuan and others by assessing the tumor-suppressive function of SETD2 in PCa, it was clearly demonstrated that SETD2 monomethylates EZH2 at its 735 lysine residue, triggering a Smurf2 E3 ligase-dependent degradation." (PMID 37228649, 2023). "In conclusion, our work reveals that the EZH2/FBXL7/PFKFB4 axis plays a regulatory role in glucose metabolism and tumor growth of NSCLC, which is expected to be potential biomarkers for NSCLC." (PMID 37179372, 2023). "Aiming to further investigate the role of EZH2 in regulating CCA progression in vivo, we established a CCA primary tumour mouse model by hydrodynamic transfection of activated forms of Akt and NICD1 plasmids into C57BL/6 mice." (PMID 38050190, 2023). "This reduction in CD8+ T cell recruitment upon CXCR3 blockade also mitigated the anti-tumor effects of combined EZH2 suppression and T/P-induced senescence and reversed PDAC tumor regressions." (PMID 37142692, 2023). "A genome-wide screen of HLA class I–low tumor cells also revealed that polycomb repressor complex 2 (PRC2) can silence HLA expression, and that in vitro PRC2 inhibition with drugs such as EZH2 inhibitors can enhance HLA expression." (PMID 37655310, 2023). "Careful monitoring of patients is required when targeting EZH2, as PRC2 can also function as a tumor suppressor." (PMID 37620312, 2023). "Thus, we hypothesized that upregulated-EZH2 may silence tumor-suppressive genes." (PMID 36622753, 2023). "Similar to the EZH2 protein, CBX7 can utilize DNA methylation machines for gene promoters and to improve quality silencing during tumor invasion." (PMID 37107631, 2023).
tumor (continued). "A screen for lncRNAs in GC patients identified LINC00628 as a tumor suppressor, and LINC00628 suppressed tumorigenesis by interacting with EZH2 and guiding PCR2 to oncogenes such as CCNA2 and HOX11, leading to their methylation and silencing." (PMID 36653445, 2023). "Further analysis revealed that CCRK is involved in the modulation of signaling networks comprising AR, Wnt, AKT, EZH2, NF-κB, and HH, and CCRK inhibitors have been found to suppress tumor proliferation." (PMID 37510333, 2023). "The qRT-PCR results demonstrated that four cellular senescence-related genes (CENPA, CXCL8, EZH2, and G6PD) and two chemokine-related genes (CCL26 and CXCL5) were overexpressed in tumor tissues from HCC patients compared with paraneoplastic tissues." (PMID 36670201, 2023). "In this review, the functions of EZH2 in HCC progression, the role of EZH2 in tumor immunity and the application of EZH2-related inhibitors in HCC therapy are summarized." (PMID 37268997, 2023). "Overexpression of EZH2 accelerated STAT3 phosphorylation at pY705, leading to tumor glycolysis, invasion, migration, and epithelial-mesenchymal transition in OSCC." (PMID 37476905, 2023). "It was reported that EZH2 directly bound to the promoter site of CHD5 and promoted trimethylation of H3K27, resulting in down-regulation of CHD5 and promoting tumor growth in HCC." (PMID 37268997, 2023). "It is evident that EZH2 plays a broad and diverse role in the regulation of tumorigenicity in GBM tumor cells, highlighting its significant clinical potential as a therapeutic target." (PMID 37205197, 2023). "IHC staining of tumor sections revealed that the levels of ALDH1, CD44, CD133, SOX2, Notch1, EZH2 and CCND1 were downregulated in CDK5RAP2-knockdown tumors." (PMID 36774351, 2023). "The present study revealed that EZH2 and TOP2A mRNAs and proteins were overexpressed in HCC tumor tissues, and their overexpression was correlated with differential tumor grade, tumor invasion, TNM stage, and shorter survival in patients with HCC." (PMID 38008711, 2023). "Combined EZH2 and DNMT1 inhibition increased effector T-cell tumor infiltration, inhibited tumor progression, and improved the therapeutic efficacy of PDL-1 blockade." (PMID 36984544, 2023). "Here we found the pancreas tumor microenvironment (TME) suppresses NK and T cell surveillance following therapy-induced senescence through EZH2-mediated epigenetic repression of pro-inflammatory SASP genes." (PMID 37142692, 2023). "Out of these 5 hub genes, only CCND1 have high median mRNA expression in normal patients than primary tumor whereas AXL, CDKN2A, TERT, and EZH2 have high expression in the primary tumor." (PMID 36715825, 2023). "BMSCs‐derived exosomes overexpressing miR‐30b‐5p were used to establish subcutaneous tumorigenesis models to study the effects of miR‐30b‐5p, EZH2 and PI3K/AKT signalling pathway on tumour growth." (PMID 37698037, 2023). "Clinically, EZH2 and TOP2A are highly expressed, and miR-139-5p is expressed at low levels in HCC tumor tissues compared with adjacent normal tissues, which indicates a poor prognosis in patients with HCC." (PMID 38008711, 2023). "Furthermore, EZH2 might participate in tumor immune evasion by T-cell exclusion and dysfunction." (PMID 36545914, 2023). "As an epigenetic regulator, EZH2 promotes HCC progression by regulating stemness, chemosensitivity, and the tumor microenvironment." (PMID 38008711, 2023). "We reanalyzed the expression data of EZH2 and TOP2A in tumor tissues and paired normal tissues from 31 tumors in the TCGA database and found that EZH2 and TOP2A were highly expressed in various solid tumors, including HCC." (PMID 38008711, 2023). "Work using ovarian cancer models demonstrated that inhibition of EZH2 induced expression of inflammatory cytokines C-X-C ligand (CXCL) 9 and CXCL10 that promoted recruitment of cytotoxic T-cells into the tumor." (PMID 36910138, 2023).
tumor (continued). "Enhancer of zeste homolog 2 (EZH2) is the enzymatic catalytic subunit of PRC2 and functions as an oncogene in tumors by promoting the H3K27me3-mediated transcriptional repression of tumor suppressor genes." (PMID 38008711, 2023). "Consistently, compared with normal tissues, EZH2 and TOP2A mRNA levels increased in HCC tumor tissues and expression of miR-139-5p decreased in HCC tumor tissues." (PMID 38008711, 2023). "Considering that CHD4 expression was positively correlated with aggressive tumour behaviour, we further focused on DNMT3B and EZH2." (PMID 36681835, 2023). "This stemness gene suppression suggests the possibility of using a continuum of Top2 catalytic inhibitors in the progression of PCa disease with the synergism of an EZH2 degrader in AR-dependent PCa cells and EZH2 catalytic inhibitors in NEPC tumor cells." (PMID 36678591, 2023). "Several factors, including EZH2, SFTPC, IGFBP5, ELN and EDN2, are regulated by NFIB, which have considerate values in the tumour microenvironment, advancing cancer impulsiveness, angiogenesis, migration and spread." (PMID 37845675, 2023). "EZH2 has been shown to exert diverse regulatory roles in GBM, modulating pathways in tumor initiation/self-renewal, differentiation, cell cycle progression, metabolism, immunogenicity, and invasiveness." (PMID 37205197, 2023). "Thus, EZH2 suppression following T/P-induced senescence triggers a phenotypic switch in the SASP program in the PDAC TME from a pro-angiogenic SASP to a pro-inflammatory SASP that may contribute to enhanced cytotoxic lymphocyte anti-tumor immunity." (PMID 37142692, 2023). "Transcriptional factor (TF) analysis highlighted the relative activation of EZH2 and CTCF in GSCL cells, and their activation was found to be correlated with tumor cell stemness, proliferation, and drug resistance." (PMID 37964983, 2023). "And also, EZH2 complex acts as a pivotal regulator of epigenetics in HCC and promotes tumor growth and metastasis during HCC development." (PMID 37689710, 2023). "Previous studies relate increased Ezh2 expression and PRC2 activity to immunoediting of the tumor environment." (PMID 36639541, 2023). "For example, LINC00673 promoted GC cell proliferation by repressing key tumor suppressors, such as KLF2 and LATS2, through its interaction with EZH2 and LSD1." (PMID 36653445, 2023). "Compared to EPZ‐6438 (tazemetostat), which is the first‐in‐class and the most widely researched oral EZH2 inhibitor, SHR2554 presented comparable anti‐tumor activity in vitro." (PMID 35841331, 2023). "EZH2 inhibitors are a rational drug target in ENKTL, although there is pre-clinical evidence that combination with agents targeted at its upstream regulators, such as JAK/STAT inhibitors, may also cause ENKTL cell death in patients with high EZH2 tumor expression." (PMID 36900160, 2023). "Of note, a piperidine derivative targeting EZH2 (enhancer of zeste homologue 2) has been reported to reduce GBM cell viability and impair tumor development and aggressiveness via an immunomodulatory mechanism." (PMID 36984801, 2023). "EZH2 knockout in PyMT and HER2-driven models demonstrated profound impact on tumor initiation, progression, and metastasis, supporting that EZH2 behaves as on oncogene by suppressing expression of tumor suppressors." (PMID 36910138, 2023). "Protein-coding genes with increased expression across all tumor types included E2F7, ETS1, EZH2, ID3/4, MKI67, PIK3R3, and TOP2A." (PMID 36865335, 2023). "In contrast, the upregulation of EZH2 observed in tumor tissue biopsies were retained in the MPM-derived cell lines, suggesting that EZH2 expression is under the control of tumor-specific factors." (PMID 36900330, 2023).
tumor (continued). "Accordingly, a growing number of studies indicate that EZH2 is also an oncogenic driver in MPM, but its effects on tumor microenvironments are still largely unexplored." (PMID 36900330, 2023). "Contrary to expectations, the deletion of EZH2 and SUZ12 in both mouse and human GR3 MB via TALEN and CRISPR-Cas9 gene editing is able to accelerate the tumor progression, suggesting a tumor suppressor activity of the protein complex in the tumor." (PMID 36968588, 2023). "Two inhibitors of EZH2, EPZ-6438 and CPI-1205, have both been applied in clinical trials for different tumours." (PMID 37194218, 2023). "Deletion of either Eed or Ezh2 disrupted PRC2 function, as both M-Smo/EedcKO and M-Smo/Ezh2cKO showed minimal H3K27me3 in tumor cells, with residual H3K27me3 in interspersed stromal cells demonstrating the effectiveness of the staining technique." (PMID 36635771, 2023). "Enzymatic inhibitors, such as 3-Deazaneplanocin A (DZNep), indirectly inhibit EZH2 by increasing the activity of S-adenosyl-L-homocysteine hydrolase (SAH), leading to apoptosis in tumor cells." (PMID 37909018, 2023). "Thus, the substantially reduced tumor growth seen in the mice treated with Taz plus B32B3 compared to the mice treated with Taz or B32B3 alone indicates that Taz in the combination treatment impaired the residual tumorigenic activities of EZH2 in the xenograft tumors." (PMID 37069142, 2023). "To understand the impact of EZH2 suppression on senescence-mediated anti-tumor immunity in PDAC, we transplanted KPC1 or KPC2 PDAC cells harboring control Renilla (shRen) or EZH2-targeting (shEzh2) shRNAs orthotopically into the pancreas of C57BL/6 mice." (PMID 37142692, 2023). "EZH2 interacts with PARP through DNA homologous recombination, DNA replication, post-translational modification and tumor immunity." (PMID 36611214, 2023). "In vivo, all GBM tumor biopsies were found to harbor HCMV with enhanced EZH2 and Myc expression, possessing a strong positive correlation between EZH2 and Myc expression as well as a strong correlation between EZH2/Myc and HCMV presence." (PMID 37147437, 2023). "Here we show that EZH2 is overexpressed in RMS patient tumours and that pharmacological inhibition of EZH2 leads to a reduction in cell proliferation and tumour spheroid volume in RMS cell models." (PMID 37858275, 2023). "To further confirm these results, we collected ten pairs of HCC and adjacent normal tissues and found that EZH2 and TOP2A protein levels were higher in tumor tissues than in adjacent normal tissues." (PMID 38008711, 2023). "Histochemical analysis revealed positive staining for both A/N+shEzh2#1, A/N+shEzh2#2 and A/N+C transfection‐induced tumour cytokeratin 19, a classical biomarker for CCA and the knockdown effects of Ezh2 were also demonstrated by histochemical staining." (PMID 38050190, 2023). "In vitro and in vivo work in a murine flank tumor model demonstrated that AC1Q3QWB, a small molecule inhibitor of EZH2’s interaction with the lncRNA HOTAIR, increases cell death and decreases tumor growth." (PMID 37205197, 2023). "In multiple MLL1-rearranged leukaemia cells, 57 depleted EZH2, EED and SUZ12 and demonstrated the significant anti-tumour effect in a variety of cancer lines and patient-derived models as well as in multiple tumour cell line xenografted and PDX models." (PMID 37667522, 2023). "NB tumor suppressor genes, including CASZ1, CLU, NGFR, and RUNX3, are direct targets of EZH2- and H3K27me3-mediated gene silencing." (PMID 38053207, 2023). "Consistent with in vitro observations, EZH2 and HDAC inhibitors exerted minimal effects on their own, but when combined triggered potent tumor regression." (PMID 37104245, 2023). "By pharmacological inhibition of either the PRC2 component EZH2 or DNMT1, it was possible to restore the tumoral CXCR3 ligand epigenetic silencing and therefore enhance CD8+ T-cell trafficking and tumor growth control." (PMID 37046597, 2023).